IL10 (interleukin 10)
Diseases named in the same sentence as IL10 in open-access papers (continued):
Sharing a sentence is not in itself a finding about the gene and the disease.
gastritis (continued). "Previously it has been reported that H. pylori induced gastritis was suppressed by adoptive transfer of Treg cells harvested from IL-10-competent C57BL/6 donor mice, demonstrating that IL-10-dependent Treg cells play a crucial role in suppressing H. pylori-induced gastric disease." (PMID 28286572, 2017). "Therefore, IL-4 and IL-10 function as protective factors in gastritis." (PMID 40264171, 2025). "It has been suggested that the ability of IFN-γ to promote macrophage secretion of pro-inflammatory cytokines, and/or to downregulate the production of anti-inflammatory factors (e.g. IL-10, transforming growth factor β), may account for the severity of gastritis in C57BL/6 mice." (PMID 27895717, 2016). "In this study, the objective is to evaluate the increase of IL-10, MMP-7 and MMP-9 in patients with H. pylori infection without any systemic disease and the correlation with the histopathologic degree of gastritis." (PMID 27703556, 2016). "The objective of this study was to investigate the serum levels of IL-10, MMP-7 & MMP-9 in gastritis patients with H. pylori infection." (PMID 27703556, 2016). "In this study, we measured the expression levels of Treg and IL-10 using ELISA and found that the peripheral blood levels of IL-10 were significantly higher in the patients with H. pylori-infected gastritis compared to the negative group." (PMID 41035878, 2025). "Although the levels of IL-5, IL-6, IL-9, IL-10, IL-13, and IL-21 were higher in patients with gastritis than Hp- group, this increase was not significant." (PMID 39807418, 2024). "In addition to IL-10, MMP9, CXCL2, and CXCL8 expression levels were significantly increased in gastritis patients compared with the control group, which was consistent with the GSE60427 and GSE5081 results." (PMID 34471638, 2021). "EPS54 also significantly alleviated the symptoms of gastritis in the H. pylori-infected mice by down-regulating the mRNA expression levels of pro-inflammatory cytokines IL-6, IL-8, IL-1β and TNF-α and up-regulating the mRNA expression of inflammatory cytokines IL-10 in gastric cells." (PMID 38978704, 2024). "In conclusion, the potential mechanism of Weibing Formula 1 in treating gastritis has the multicomponent, multitarget, and multiway characteristics, and PTGS2, NOS2, EGFR, MMP9, CXCL2, CXCL8, and IL-10 may be the important direct targets of Weibing Formula 1 in gastritis treatment." (PMID 34471638, 2021). "Hence we found a positive correlation between severity of gastritis and no of Foxp3+ cells as well as IL-10 and TGF-β expression." (PMID 28286572, 2017). "EPS54 could also effectively alleviate the gastritis in the H. pylori-infected mice by down-regulating the mRNA expression levels of pro-inflammatory cytokines IL-6, IL-8, IL-1β and TNF-α and up-regulating the mRNA expression of inflammatory cytokine IL-10 in gastric cells." (PMID 38978704, 2024). "In patients with non-ulcer dyspepsia, gastritis or peptic ulcers that were infected by H. pylori, a high secretion of IL-17, IFN-γ, IL-23, IL-6, IL-10, TNF-α, IL-21, IL-8, and IL-37 was reported." (PMID 35955936, 2022). "Moreover, other inflammatory cytokines and chemokines (IL-27, IFN-β, IL-1α, IL-23, IL-22P70, TNF-α, IL-17A, IL-10, IL-1β, and MCP-1) were not showed dose-dependent changed in DFMO-treated mice compared to gastritis mice group." (PMID 32231118, 2020). "Treg may produce sufficient levels of IL-10 and transforming growth factor (TGF)-β to attenuate responses rather than to prevent gastritis totally." (PMID 25950510, 2015). "In parallel, H. pylori-administered mice demonstrated gastritis with inflammatory responses, as indicated by the prominent histological scores based on inflammatory cell infiltration and epithelial damage and increased inflammatory cytokines (IL-6 and TNF-α, but not IL-10) in the stomach." (PMID 35955701, 2022).
HCMV infection (34 papers, 2011 to 2025). "Increased IL-10 production during HCMV infections in transplant patients is linked with HCMV disease." (PMID 36445084, 2022). "In a Finnish renal transplant cohort, the donor interleukin-10 (IL-10) gene polymorphism −1082AA was observed to influence HCMV infection risk." (PMID 31396258, 2019). "IL-10 deficiency also increases hepatic immunopathology, leading to more severe disease and weight loss during acute murine cytomegalovirus infection." (PMID 28810829, 2017). "IL-10 deficiency increases hepatic damage, and leads to more severe disease during acute murine cytomegalovirus infection." (PMID 28810829, 2017). "These factors include GCSF and IL10, both of which have been linked to hCMV infection including viral latency and reactivation." (PMID 27387064, 2016). "The expression of cmvIL-10, encoded by the UL111A gene, during productive HCMV infection is known to upregulate host IL-10 production in monocytes via phosphatidylinositol 3-kinase (PI3K)/signal transducer and activator of transcription 3 (STAT3) signaling pathway." (PMID 33013921, 2020). "Interestingly, it has also been shown that changes in serum IL-10 expression due to polymorphisms in the IL-10 gene positively correlate with the risks of HCMV infection and disease in transplant recipients." (PMID 28628650, 2017). "In addition to chemokines, a recent study showed that a deficiency of interleukin-10 (IL-10) can reduce lymphocyte infiltration to the brain during cytomegalovirus infection via up-regulating the expression of CXCL9 and CXCL10." (PMID 26610549, 2015). "Studies related to chronic viral infections, such as cytomegalovirus infections, have shown that blocking IL-10 favors the antiviral activity of T cells, leading to viral eradication." (PMID 41417343, 2025). "Longitudinal samples from seven primary HCMV infections (donor seropositive, recipient seronegative (D+R−) kidney transplant patients) were also studied for the IL-10 responses to a broad range of pooled HCMV proteins." (PMID 36558866, 2022). "Our analysis of when during HCMV infection IL-10 CD8+ T cells arise revealed distinct differences in the HCMV proteins generating an IL-10 response in CD8+ T cells present in the peripheral blood." (PMID 36558866, 2022). "While IL-10 is classically considered anti-inflammatory, NK cell-derived IL-10 has been shown to prevent tissue damage that occurred during murine cytomegalovirus infection and to promote proliferation and cytotoxicity of human CD8+ T cells." (PMID 36618376, 2022). "There are limited reports on IL-10 secretion by CD8+ T cells in HCMV infection but liver transplant recipients who progressed to CMV disease had increased expression of PD-1 on both CD4+ and CD8+ T cells and increased IL-10 in their plasma." (PMID 36558866, 2022). "Fifthly, it is generally acknowledged that interleukin (IL)-10 produced by regulatory T cells (Tregs) plays an important role in suppressing immune responses during HCMV infection." (PMID 33808294, 2021). "The results showed that HCMV infection significantly increased host IL-10 synthesis and promoted the proliferation of M. massiliense in an IL-10-dependent manner." (PMID 33013921, 2020). "In patients with active HCMV infection i.e. group 1 and group 2, mean concentrations of IFNγ, IL10 and IL8 were found to be quite similar." (PMID 32985571, 2020). "On the other hand, analyses of IL-10, which is a typical Th2-type cytokine, showed a moderate increase after HCMV infections, but more so after reactivations (n.s.)." (PMID 30524448, 2018). "One effect of HCMV infection is the induction of the cytokine IL-10, a secreted protein that suppresses many antiviral responses." (PMID 28628650, 2017). "Data obtained from the MCMV model has demonstrated an important protective role for cellular IL-10 during acute CMV infection." (PMID 27926930, 2016).
HCMV infection (continued). "Earlier studies have also shown that mouse cytomegalovirus infection resulted in premature and transient activation of host IL-10 very early during infection resulting in a significant and selective reduction of MHCII expression on cell surface." (PMID 27689097, 2016). "There has been extensive characterization of the HCMV-specific CD8+ T cell response to HCMV infection but few studies have addressed whether the secretion of IL-10 also occurs." (PMID 36558866, 2022). "Interleukin-10 (IL-10) is an immunosuppressive cytokine induced during HCMV infection." (PMID 36445084, 2022). "Active HCMV infection may aggravate the inflammatory microenvironment by increasing production of inflammatory factors such as viral IL-10, tumor necrosis factor-α, transforming growth factor-β and prostaglandins." (PMID 32322296, 2020). "Human and CMV IL-10 expression is upregulated in CMV infection." (PMID 33374185, 2020). "The induction of high levels of IL-10 during acute HCMV infections has been speculated to power other immunosuppressive properties of HCMV." (PMID 28628650, 2017). "Levels of the anti-inflammatory cytokine IL-10 increase during both productive and latent stages of infection, which may be important for the establishment and maintenance of a stable HCMV infection." (PMID 28628650, 2017). "Consequently, the relative numbers of CD4+ T effector and memory cells that produce IFN-γ and IL-10 during the various phases of CMV infection likely form an axis that regulates the magnitude, duration, and reactivation of CMV in both mice and men." (PMID 28647908, 2017). "Levels increase of the anti-inflammatory cytokine IL-10, which may be important for the establishment of HCMV infections and is required for the development of high viral titres by murine cytomegalovirus." (PMID 28628650, 2017). "IL-10 production induced by HCMV infection is also in part mediated by pUL11." (PMID 28628650, 2017). "Two isoforms of viral IL-10 exist, both of which suppress immune cell activation in vitro and induce expression of cellular IL-10, suggesting the importance of the immune suppressive functions of IL-10 in HCMV infection in vivo." (PMID 27926930, 2016). "Although it remains to be determined whether viral IL-10 plays any role in HCMV infection of DCs, it is possible that any viral IL-10-mediated upregulation of DC-SIGN may enhance virus entry into DCs." (PMID 25071749, 2014). "Importantly, further studies verifying the expression of the other HCMV IL-10 transcripts (C to H) identified in infected cells are necessary to determine if they are expressed during natural infection and if they have specific functions during HCMV infection." (PMID 40284944, 2025). "In addition, the data could be informative for monitoring the progression of HCMV infection and identifying patients at risk of HCMV disease since viral IL-10 has a severe potential to impair the host immune response." (PMID 40284944, 2025). "IL-10 induction during HCMV infections may also have wider effects on immune responses." (PMID 36445084, 2022). "In patients with active HCMV infection, i.e. group 1 and group 2, the mean concentrations of CRP, IL6, IL10 and MCP1 were found to be quite similar but significantly varied from group 3 patients." (PMID 35538132, 2022). "We have previously shown that experimental latent HCMV infection of CD34+ progenitor cells alters the cellular secretome resulting in the upregulation of chemokines CCL8, CCL2 and secretion of TGF-β and cellular IL-10 (cIL-10)." (PMID 33912186, 2021). "Cytomegalovirus infection has been shown to downregulate MMP activity directly and indirectly through the expression of CMV IL-10 and the upregulation of IL-10." (PMID 33374185, 2020). "As pUL11 perturbs CD4 T cell function and induces IL-10, which can directly limit CD4 T cell activation and expansion, we investigated whether the presence of pUL11 can influence CD4 T cell control of an HCMV infection." (PMID 36445084, 2022).
HCMV infection (continued). "HCMV infection is known to promote a cellular secretome that modulates its micro-environment by increasing the production of relevant immunosuppressive mediators, such as TGF-β-expressing Tregs and IL-10." (PMID 33808294, 2021). "Indeed, blood IL-10 and IFN-γ concentrations are high in hCMV infection and in chronic hCMV infection." (PMID 24839609, 2014). "Interestingly, HCMV infection does not induce but rather represses ZFP36 expression to maintain high levels of IL-10 transcription and secretion." (PMID 37830871, 2023). "When males and females were analysed separately in our study, we found that HCMV+ females had reduced TNF-α and TNF-α:IL-10 to HKLM stimulation, but there was no such effect of HCMV infection in males." (PMID 32707906, 2020). "The lack of impact of HCMV infection on measles-specific innate pro-inflammatory cytokines IL-1β and TNF, the Th1 cytokine IFN-γ, the Th2 cytokine IL-4 and the anti-inflammatory cytokine IL-10 is encouraging." (PMID 32582177, 2020).
sarcoidosis (34 papers, 2010 to 2025). Sarcoidosis is a multisystemic disorder of unknown cause characterized by the formation of immune granulomas in involved organs. "We evaluated MIF in the serum and bronchoalveolar lavage (BAL) fluid of sarcoidosis patients in association with clinical features and cytokines, IL-18, IL-10, IL-6, IFN-γ." (PMID 36207373, 2022). "In the present study, we evaluated the association of multiple SNPs in IL10 in Japanese sarcoidosis patients." (PMID 22393278, 2012). "The aim of the current study was to investigate whether IL10 polymorphisms affect the development of Japanese patients with sarcoidosis." (PMID 22393278, 2012). "However, further genetic studies in other ethnic populations are required to elucidate the association between IL10 polymorphisms and sarcoidosis." (PMID 22393278, 2012). "Within most Th1-dominant mycobacterial granuloma models, unchanged secretion levels of IL-10 were observed while significantly elevated secretion of IL-10 was observed across studies using Schistosoma or Candida antigens or in studies focusing on sarcoidosis." (PMID 35269486, 2022). "As our current data in sarcoidosis indicate that MIF levels are positively associated with IFN-γ and IL-10, but negatively associated with IgG level." (PMID 36207373, 2022). "In contrast, higher serum levels of IL-10 were found in patients with IPF than normal subjects, and the highest level of IL-10 in the bronchoalveolar lavage was demonstrated in patients with IPF compared with sarcoidosis or hypersensitivity pneumonitis." (PMID 34830373, 2021). "A study on blood monocytes showed a decrease in IL-10-producing regulatory monocytes in sarcoidosis patients compared with healthy controls, further strengthening the pro-inflammatory role of monocytes." (PMID 33446605, 2021). "Phenotyping B-cell populations in sarcoidosis patients revealed that circulating numbers of IL-10 producing B-cells were elevated in patients with active sarcoidosis." (PMID 32760396, 2020). "Although current knowledge of IL-10 producing B-cells is insufficient to draw any conclusion on the role of Bregs, it seems that there is an altered B-cell homeostasis in active sarcoidosis." (PMID 32760396, 2020). "After co-stimulation of PBMCs with FCWAs and LPS, the production of TNF-α, IL-6, IL-10 and IL-12 was significantly higher in patients with sarcoidosis, compared to healthy subjects (1.7-fold, 2.0-fold, 2.2-fold, and 2.8-fold, respectively; all p < 0.05)." (PMID 27688795, 2016). "We demonstrated previously that after in vitro stimulation of PBMCs with FCWAs alone, the secretion of TNF-α, IL-6, IL-10 and IL-12 was higher in patients with sarcoidosis compared to healthy subjects." (PMID 27688795, 2016). "A recent study showed that IL‐10 producing B cells (or ‘‘B reg cells’’) were increased in sarcoidosis 17, resonating the findings of increased FoxP3 Treg cells in this condition." (PMID 24723379, 2014). "Focusing on IL‐10‐producing monocytes, we first showed that monocytes isolated from the peripheral blood of corticosteroid‐naïve sarcoidosis patients (n = 51) produced less IL‐10 compared to controls, and were less able to suppress T‐cell proliferation." (PMID 24723379, 2014). "At a high environmental exposure to fungi, the level of serum IL-10 among subjects with sarcoidosis was low." (PMID 25180094, 2014). "The aim of the study was to further investigate the serum levels of IL-10 in patients with sarcoidosis and relate them to fungal exposure in terms of the amount of fungi in the air of their homes and β-glucan in bronchoalveolar lavage (BAL) fluid." (PMID 25180094, 2014). "In conclusion, our study shows that IL‐10 production and T‐cell regulation capabilities by monocytes are defective in patients with sarcoidosis." (PMID 24723379, 2014). "At high levels of fungal exposure patients with sarcoidosis have a depressed secretion of the anti-inflammatory cytokine IL-10." (PMID 25180094, 2014).